GAS6 (growth arrest specific 6)
Diseases named in the same sentence as GAS6 in open-access papers (continued):
Sharing a sentence is not in itself a finding about the gene and the disease.
pancreatic cancer (continued). "Beyond inhibiting epithelial mesenchymal transition of pancreatic tumor cells, targeting Gas6 promotes the antitumor immune response mediated by NK cells." (PMID 32708142, 2020). "Since this Gas6-dependent immune regulation of NK cells is also conserved in humans, anti-Gas6-Axl therapies are likely to promote anti-tumor immunity, via NK cell activation, in pancreatic cancer patients." (PMID 32174917, 2020). "This study supports the rationale for targeting Gas6 in pancreatic cancer and use of NK cells as a potential biomarker for response to anti-Gas6 therapy." (PMID 32174917, 2020). "Pancreatic tumor tissues from control and anti-Gas6 treated mice were stained with picrosirius red to assess collagen deposition and for αSMA+ cells." (PMID 32174917, 2020). "We found that both F4/80+/CD206+ (M2-like macrophages) and αSMA+ stromal cells are the main sources of Gas6 in pancreatic tumors." (PMID 32174917, 2020). "To further investigate the effect of anti-Gas6 on vimentin expression in pancreatic cancer cells in our in vivo tumor model, we analyzed vimentin protein expression in pancreatic tumor tissues from control and anti-Gas6 treated mice." (PMID 32174917, 2020). "Our studies show that inhibition of Gas6 signaling in pancreatic cancer not only affects the tumor cells but notably affects the NK cells." (PMID 32174917, 2020). "In these studies, we sought to understand the effect of Gas6 blockade in both the tumor and the stroma/immune compartments, in vivo, in pancreatic cancer." (PMID 32174917, 2020). "Our data suggest that Gas6 simultaneously acts on both the tumor cells and the NK cells to support pancreatic cancer metastasis." (PMID 32174917, 2020). "Pancreatic tumor tissues from control and anti-Gas6 treated mice were stained with the endothelial marker CD31." (PMID 32174917, 2020). "This study provides further mechanistic insights into the mode of action of anti-Gas6 therapies and suggests the use of NK cells as an additional biomarker for response to anti-Gas6 therapies in pancreatic cancer patients." (PMID 32174917, 2020). "Chemotherapy combined with Gas6/AXL targeted therapy may provide new hope for metastatic pancreatic cancer." (PMID 40538442, 2025). "Indeed, chemotherapy has been reported to increase the infiltration of neutrophils in pancreatic cancer and results in metastasis via Gas6/AXL signaling." (PMID 38654356, 2024). "Our findings indicate that GAS6-CAR-T-cell therapy may be effective for pancreatic cancers with low toxicity." (PMID 37475048, 2023). "Notably, GAS6 acts on both tumor cells and NK cells simultaneously, facilitating metastatic activities in pancreas cancer." (PMID 37313463, 2023). "We next assessed the capacity of GAS6-CAR-T cells to kill TAM-positive pancreatic cancer cells." (PMID 37475048, 2023). "Thus, GAS6-CAR-T cells can effectively target pancreatic cancer cell with gemcitabine resistance induced by TAM overexpression." (PMID 37475048, 2023). "Uncarboxylation of Gas6 with warfarin increases pancreatic cancer cell growth and metastases." (PMID 34836355, 2021). "Gaining a better understanding of how blockade of Gas6 signaling affects pancreatic cancer is important because it will help design and interpret the results of the recently launched clinical trials that are testing anti-Gas6/TAM receptors therapies in pancreatic cancer patients." (PMID 32174917, 2020). "Similar to what we observed with the anti-Gas6 treatment, warfarin reduced pancreatic cancer metastasis to the lungs and increased the number and activation of NK cells in lungs and mesenteric lymph nodes, as shown by the increase in NKp46+ and granzyme B expression." (PMID 32174917, 2020). "To test this hypothesis we evaluated NK cells in primary pancreatic tumors, tumor draining lymph nodes, and metastatic lesions of mice treated with control IgG or anti-Gas6 antibody." (PMID 32174917, 2020).
pancreatic cancer (continued). "The data presented in this study describe a dual anti-tumor effect of Gas6 blockade in pancreatic tumors, shedding light on the anti-cancer mechanism of action of inhibitors of the Gas6-Axl pathway and supporting the rationale for using anti-Gas6 therapy in pancreatic cancer patients." (PMID 32174917, 2020). "Thus, inactivation of Gas6 signaling can promote anti-tumor immunity, via NK cell activation, in pancreatic tumors." (PMID 32174917, 2020). "In our study we found that both TAMs and CAFs are the main sources of Gas6 in pancreatic tumors." (PMID 32174917, 2020). "Inspired by this study, we investigated whether, in our pancreatic cancer model, Gas6 blockade supports the activation of T cells." (PMID 32174917, 2020). "Pancreatic tumors are usually poorly vascularized but since Gas6 signaling can support endothelial cells proliferation and vascularization we next evaluated whether anti-Gas6 therapy could affect angiogenesis in pancreatic tumors." (PMID 32174917, 2020). "Since fibrosis and collagen deposition have been suggested to re-strain the metastatic spreading of pancreatic cancer cells, we next investigated whether Gas6 blockade could affect fibroblasts and collagen deposition in pancreatic tumors." (PMID 32174917, 2020). "Consequently, GAS6 has been proposed as a therapeutic target for pancreatic cancer." (PMID 37313463, 2023). "Thus, the GAS6-CAR-T cells appear to specifically target TAM-positive pancreatic cancer cells." (PMID 37475048, 2023). "Thus, next, with the aim to understand the systemic effect of Gas6 blockade in myeloid cells and T cells in pancreatic cancer, we evaluated the number and activation status of myeloid cells and T cells in pancreatic tumors, blood and metastatic tissues using mass and flow cytometry." (PMID 32174917, 2020). "To determine whether the reduced metastasis observed when we block Gas6 was caused by an effect on tumor cell EMT, we evaluated the expression of EMT markers and transcription factors on tumor cells from pancreatic tumors treated with isotype control antibody or Gas6 blocking antibody." (PMID 32174917, 2020). "Thus, we next hypothesized that the anti-metastatic effect of Gas6 blockade we observe in our pancreatic cancer model could be due to a re-activation of NK cells." (PMID 32174917, 2020). "This latter idea might offer a molecular explanation that the in vivo administration of warfarin could block the Gas6-Axl signaling complex in a pancreatic cancer model, as well as that warfarin exerts an antimetastatic action in mice via the Cbl-Gas6-TAM axis in NK cells." (PMID 29176978, 2017). "Overall, our results demonstrate that eEF2K mediates interactions between pancreatic cancer cells and TAMs through MCP-1/Gas6 signaling and exosomal communication, promoting tumor growth and progression." (PMID 40624025, 2025). "These suggest that GAS6-based CAR-T cells can be a promising and safe therapeutic strategy for pancreatic cancer." (PMID 37475048, 2023). "Another study has shown that inhibiting growth arrest-specific protein 6 (Gas6), a multifunctional protein secreted by TAMs and CAFs, resulted in inhibiting EMT and metastases in pancreatic cancer." (PMID 34298815, 2021). "Inhibition of the Gas6-Axl pathway has been shown to reverse EMT, tumor migration and intra-tumoral micro-vessel density in pancreatic cancer." (PMID 32174917, 2020). "Importantly, ROC statistical analysis of the plasma levels of sAXL, GAS6, or CA19-9 (a marker of pancreatic cancer) in two studied cohorts revealed that sAXL outperformed CA19-9 for discriminating between CP and PDAC." (PMID 37469409, 2023). "A Gas6 blockade decreased the epithelial–mesenchymal transition (EMT) in pancreatic cancer cells, while neither myeloid cells nor T cells were affected." (PMID 35453676, 2022).
pancreatic cancer (continued). "To further investigate the effect of inhibiting Gas6-Axl signaling in pancreatic cancer progression and metastasis, we performed another in vivo experiment, using our syngeneic orthotopic KPC model using warfarin (instead of a neutralizing anti-Gas6 antibody)." (PMID 32174917, 2020). "NK cells were almost absent in all primary tumors from both anti-Gas6 and control treated mice (except for one anti-Gas6 treated pancreatic tumor)." (PMID 32174917, 2020). "While the cancer cell autonomous functions of Gas6 are well-documented, the effect of Gas6 signaling in the stroma/immune compartment in pancreatic cancer has not been fully explored." (PMID 32174917, 2020). "Therefore, we choose the pancreatic cancer patient-derived xenograft (PDX) models with the high expression of AXL in both cancer cell and macrophage to test whether GAS6-CAR-T cells can also eliminate cancer cells and macrophages in vivo." (PMID 37475048, 2023). "Taken together, these findings suggest that chemotherapy-induced neutrophil accumulation and upregulation of Gas6 also occurs in liver metastasis of patients with CRC and thus, targeting Gas6 might improve therapeutic interventions in patients with pancreatic cancer and CRC." (PMID 35022267, 2022). "In the study of Ireland and colleagues, the blockade of GAS6 using warfarin in pancreatic models further revealed that inhibition of the GAS6/AXL axis could reduce cancer cell plasticity, activate NK cells and inhibit pancreatic cancer metastasis." (PMID 35572601, 2022). "So far many studies have focused on the cancer-cell autonomous role of Gas6 and based on their effect on tumor cell proliferation and plasticity several inhibitors of the Gas6-Axl pathways, including warfarin (clinical trial ID: NCT03536208) are currently being tested in pancreatic cancer patients." (PMID 32174917, 2020). "However, the role of Gas6 in pancreatic cancer metastasis has not been fully investigated." (PMID 32174917, 2020). "D9 and E8 induced the suppression of Gas6-mediated phosphorylation of AXL and conducted via receptor down-regulation and internalization irrespective of Gas6 in pancreatic cancer cells and xenograft models." (PMID 35311091, 2022). "We found that blocking of Gas6 significantly decreased the expression of the EMT transcription factors Snail 1, Snail 2, and Zeb 2, while twist 1 and Zeb 1 levels remained unchanged and twist 2 was not expressed in pancreatic cancer cells." (PMID 32174917, 2020).
melanoma (20 papers, 2016 to 2025). A malignant, usually aggressive tumor composed of atypical, neoplastic melanocytes. "The spatial organization of high-risk melanoma cells and GAS6 + macrophages further underscores the importance of spatially defined niches in mediating tumor-immune crosstalk, a concept increasingly recognized in cancer biology." (PMID 41034991, 2025). "Combining myeloid-GAS6 ablation with immune checkpoint blockade overcomes therapy resistance, offering a precision strategy for high-risk melanoma." (PMID 41034991, 2025). "Survival analysis demonstrated that the combination of Myeloid-GAS6 KO and α-PD-1 therapy significantly improved survival rates in melanoma-bearing mice." (PMID 41034991, 2025). "Collectively, our results reveal that GAS6 + macrophages enhance glycolysis and oxidative phosphorylation to fuel GAS6 secretion, which interacts with high-risk TEAD3 + melanoma cells via the TYRO3 receptor." (PMID 41034991, 2025). "In vivo, intravenous injection of treated melanoma cells revealed that GAS6 + macrophage co-culture and GAS6 treatment significantly increased tumor fluorescence intensity and weight compared to controls, whereas TYRO3 inhibition suppressed tumor growth." (PMID 41034991, 2025). "To further confirm Gas6 specifically activates Axl, we applied Gas6 on another melanoma cell line WM983B in which Axl is undetectable." (PMID 36989239, 2023). "We incubated melanoma cells in quiescence media containing 0.5% dialyzed FBS with 500 ng/ml of Gas6 for 24h to determine the effect of Gas6 on the migration of melanoma cells." (PMID 36989239, 2023). "It is thus tempting to propose that the actions of the GAS6/AXL signaling contribute to PCSK9-initiated immunosuppressive TME in melanoma." (PMID 36588164, 2023). "PDGF and growth arrest-specific 6 (GAS6) proteins induce CDRs in mouse melanoma 2054E and human glioblastoma LN299 cells, respectively." (PMID 35799301, 2022). "Stimulation of melanoma cells with GAS6 has been reported to activate several downstream signaling pathways including MAPK, AKT, and JAK/STAT." (PMID 32042425, 2020). "These include two different mouse monoclonal antibodies raised against the extracellular domain of human TYRO3 that block GAS6-induced TYRO3 signaling in melanoma cells and have low cross-reactivity with MERTK and AXL." (PMID 30501104, 2018). "To investigate how GAS6 secretion interacts with TEAD3 + melanoma cells, we isolated TEAD3 + tumor cells from a B16F10luc melanoma mouse model and treated them with either GAS6 or PBS (control) during vitro culture, followed by non-targeted metabolomics sequencing." (PMID 41034991, 2025). "Functional assays demonstrated that Mmut knockdown reversed the GAS6-induced enhancement of migration in TEAD3 + melanoma cells, indicating that GAS6 promotes melanoma cell aggressiveness by dysregulating propionate metabolism through Mmut upregulation and methylmalonic acid accumulation." (PMID 41034991, 2025). "To validate the single-cell RNA sequencing results, we isolated GAS6 + macrophages from B16F10luc-induced syngeneic melanoma tumors and adjacent normal tissues using flow cytometry, revealing a significantly higher proportion of GAS6 + macrophages in tumor tissues." (PMID 41034991, 2025). "Collectively, these findings reveal a critical metabolic-immune crosstalk whereby GAS6 reprograms propionate metabolism in TEAD3 + melanoma cells via Mmut-mediated MMA accumulation, which not only enhances cell aggressiveness but also fosters an immunosuppressive microenvironment." (PMID 41034991, 2025). "Furthermore, we demonstrated that myeloid-specific GAS6 knockout enhances the efficacy of anti-PD-1 therapy, providing a novel strategy to overcome immunotherapy resistance in melanoma." (PMID 41034991, 2025).
melanoma (continued). "To investigate the role of the GAS6-TYRO3 axis in melanoma progression and its impact on immunotherapy efficacy, we generated myeloid-specific GAS6 knockout (Myeloid-GAS6 KO) mice and established a melanoma model by injecting tumor cells into these mice and wild-type (WT) controls." (PMID 41034991, 2025). "That study also found that transcriptional upregulation of Gas6 could be detected in the microenvironment of melanoma and breast cancer tumors." (PMID 27775650, 2016). "Next, we were interested in whether Gas6 promotes the migration of melanoma cells." (PMID 36989239, 2023). "Knockdown of Mmut in TEAD3 + melanoma cells significantly reduced methylmalonic acid levels in both PBS- and GAS6-treated groups." (PMID 41034991, 2025). "For example, in melanoma, FAK in pericytes negatively regulates Gas6/Axl signaling to inhibit tumor angiogenesis and tumor growth." (PMID 37206921, 2023). "Expression of Tnf, Il1b, Pros1, and Gas6 was enhanced upon tumor growth in vivo, as was Dkk1, in contrast to studies showing down-regulation of DKK genes in melanoma cell lines in vitro, relative to melanocytes." (PMID 37043573, 2023). "Gas6 induces ERK signaling by interacting with AXL and promotes melanoma cell proliferation." (PMID 37265798, 2023). "In this study, we profile the expression of MER, TYRO3, and AXL among multiple human cancer cells, and assess induction of phosphorylated AKT (pAKT) by GAS6 and reversal by AXL/MER inhibitors in human melanoma G361 cells that were found to express high levels of MER and TYRO3, but not AXL." (PMID 32042425, 2020).
atherosclerosis (18 papers, 2013 to 2025). A disease characterized by the build-up of fatty material and calcium deposition in the arterial wall resulting in partial or complete occlusion of the arterial lumen. "We claimed significance at FDR of 0.05 and identified various complex traits significant, including ischemic heart disease for the CETP variant and heart failure/atherosclerosis, hypercholesterolemia traits for GAS6 variant." (PMID 36220816, 2022). "The group also includes the inflammation marker CRP, which is elevated in both obesity and CVD, and GAS6, which has been implicated in atherosclerosis, thrombosis and innate immune reactions." (PMID 35454109, 2022). "Other mutations in MERTK and its opsonin, Gas6, are associated with increased susceptibility towards atherosclerosis and autoimmune disorders including multiple sclerosis and SLE." (PMID 34065321, 2021). "Similar to multiple sclerosis, polymorphisms in MERTK and Gas6 are also associated with atherosclerosis." (PMID 34065321, 2021). "The Gas6/Axl pathway has also been implicated in in the development of vascular calcification, vascular remodeling and atherosclerosis." (PMID 32717722, 2020). "There is increasing interest in Gas6, given that the Gas6/Axl survival pathway has been implicated in the pathophysiology of atherosclerosis." (PMID 24236135, 2013). "Several studies have implicated GAS6 in (premature) atherosclerosis." (PMID 37194071, 2023). "In an association analysis of seven miRNAs with the GAS6 mRNA the free energy interaction of the miRNAs with the mRNA is more than −130 kJ/mole, which indicates that these associations are promising markers of atherosclerosis." (PMID 33329752, 2020). "Ultimately, PS, Gas6, and TAM receptors present an exciting avenue of potential therapeutic targets against inflammation associated with atherosclerosis and cardiovascular disease." (PMID 39684449, 2024). "Recent studies have indicated that Gas6/Axl participated in the development of vascular calcification, vascular remodeling and atherosclerosis." (PMID 32717722, 2020). "Gas6 and its receptors are involved in the pathogenesis of neointima formation, vasculitis and atherosclerosis." (PMID 24572151, 2014). "Gas6 has been shown to play a pivotal role in pathophysiological processes such as atherosclerosis, cancer, and thrombosis through activation of cells ranging from platelets to endothelial cells, as well as vascular smooth muscle cells." (PMID 24409287, 2014). "Furthermore, EMP-derived macrophages expressed high levels of stabilin 1 (Stab1) and growth arrest specific 6 (Gas6), both of which are important for efferocytosis, a process crucial for the inhibition of atherosclerosis." (PMID 34759917, 2021). "Further experiments in humans are required to form conclusions as to whether Gas6 may be a reliable pharmacological target in thrombosis, hemostasis, restenosis, and atherosclerosis." (PMID 25805676, 2015). "By contrast, GAS6 (growth arrest-specific gene 6) has a strong relevance to atherosclerosis." (PMID 23372645, 2013). "The ligands of these receptors, Protein S (PS) and growth arrest specific protein 6 (Gas6), are essential for TAM receptor functions in the amplification and resolution of atherosclerosis." (PMID 39684449, 2024). "The growth arrest-specific 6 (GAS6) gene and its receptor, AXL, are pivotal in vascular hemostasis and the pathogenesis of atherosclerosis." (PMID 39845086, 2024). "Thus, soluble Axl may influence atherosclerosis pathology by a soluble Axl/Gas6/Mer axis." (PMID 39684449, 2024). "Estrogen (E2), via the estrogen receptor α (ERα), stimulates Gas6 transcription to inhibit vascular smooth muscle cell (VSMC) apoptosis and calcification, advanced atherosclerosis, and vascular calcification." (PMID 39684449, 2024).